OTUD4 (OTU deubiquitinase 4)
Description:
Deubiquitinase which hydrolyzes the isopeptide bond between the ubiquitin C-terminus and the lysine epsilon-amino group of the target protein. May negatively regulate inflammatory and pathogen recognition signaling in innate immune response. Upon phosphorylation at Ser-202 and Ser-204 residues, via IL-1 receptor and Toll-like receptor signaling pathway, specifically deubiquitinates 'Lys-63'-polyubiquitinated MYD88 adapter protein triggering down-regulation of NF-kappa-B-dependent transcription of inflammatory mediators. Independently of the catalytic activity, acts as a scaffold for alternative deubiquitinases to assemble specific deubiquitinase-substrate complexes. Associates with USP7 and USP9X deubiquitinases to stabilize alkylation repair enzyme ALKBH3, thereby promoting the repair of alkylated DNA lesions.
Synonyms: KIAA1046; HSHIN1; DUBA6; HIN1
Tractability: PROTAC: ubiquitination databases record sites on it; its protein half-life has been measured.
Gene: Protein-coding gene on chromosome 4 (145,110,838 to 145,180,621, reverse strand). Ensembl gene ENSG00000164164.
Subcellular location: Cytoplasm; Nucleus
Subcellular location (Human Protein Atlas): Cytosol
Gene Ontology:
Molecular function: cysteine-type deubiquitinase activity; K63-linked deubiquitinase activity; molecular adaptor activity; protein binding; RNA binding
Biological process: antiviral innate immune response; DNA alkylation repair; negative regulation of interleukin-1-mediated signaling pathway; negative regulation of toll-like receptor signaling pathway; protein K11-linked deubiquitination; protein K48-linked deubiquitination; protein K63-linked deubiquitination; regulation of protein K48-linked deubiquitination
Cellular component: cytoplasm; cytosol; nucleus
Genetic constraint (gnomAD): Loss-of-function variants: 15 observed, 78.06 expected, observed/expected ratio (o/e) 0.19, 90% interval 0.13 to 0.3. The upper end of that interval is the gene's LOEUF score, 0.3, which puts it in group 1 of 6, group 1 being the genes least tolerant of losing a copy. Missense variants: 814 observed, 1,020.1 expected, observed/expected ratio (o/e) 0.8, 90% interval 0.75 to 0.85. Synonymous variants: 354 observed, 380.16 expected, observed/expected ratio (o/e) 0.93, 90% interval 0.85 to 1.02.
Homologues: Orthologues: chimpanzee OTUD4 (99% identical), macaque OTUD4 (99% identical), dog OTUD4 (91% identical), pig OTUD4 (89% identical), mouse Otud4 (87% identical), rat Otud4 (87% identical), guinea pig OTUD4 (86% identical), rabbit OTUD4 (86% identical), tropical clawed frog otud4 (45% identical), zebrafish otud4 (30% identical), Drosophila melanogaster otu (20% identical), Drosophila melanogaster CG3251 (11% identical), and 2 more. Paralogues in human: OTUD5 (11% identical), OTUD3 (7% identical), OTUD1 (5% identical), OTUD6B (3% identical), OTUD6A (3% identical).
Diseases named in the same sentence as OTUD4 in open-access papers:
OTUD4 is named in the same sentence as 53 diseases in open-access papers, as found by Europe PMC text mining. Sharing a sentence is not in itself a finding about the gene and the disease. The quoted sentences say what the papers report.
breast carcinoma (8 papers, 2020 to 2025). "Of clinical relevance, elevated OTUD4 expression is associated with poorer outcomes in breast cancer and facilitates TGF-β signaling—a pathway critically involved in epithelial–mesenchymal transition (EMT) and metastatic dissemination." (PMID 41297414, 2025). "The DNA methyltransferase DNMT1 induces hypermethylation of the promoter of MEG3 and inhibits its expression, which then promotes the growth of breast cancer cells through the regulation of the miR-494-3p/OTUD4 axis." (PMID 41050073, 2025). "Engineered 4T1 control and 4T1 OTUD4–OE breast cancer cells were subcutaneously injected into the mammary fat pad of female BALB/C mice." (PMID 38530357, 2024). "OTU deubiquitinase 4 (OTUD4) is a potential predictive factor for several cancers such as breast cancer, liver cancer, and lung cancer." (PMID 38429268, 2024). "Collectively, our findings uncover what we believe to be a novel strategy for targeting the immunosuppressive OTUD4/CD73 proteolytic axis in treating immune-suppressive breast cancers with the inhibitor ST80." (PMID 38530357, 2024). "Pharmacological suppression of the OTUD4/CD73 proteolytic axis revives antitumor immunity against immune-suppressive breast cancers in mouse models." (PMID 38530357, 2024). "Herein, we measured DNMT1, MEG3, miR-494-3p and OTUD4 expression, verified the interaction between them, and then discussed the impact of them on biological function of breast cancer cells." (PMID 35109842, 2022). "We revealed for the first time that MEG3 regulated OTUD4 in breast cancer cells through competitively binding of miR-494-3p, thus regulating growth of breast cancer cells." (PMID 35109842, 2022). "Briefly, our results demonstrated that, DNMT1 induced methylation of MEG3 promoter, and played a key role in breast cancer growth throughmiR-494-3p/OTUD4 axis." (PMID 35109842, 2022). "DNMT1 and miR-494-3p were highly expressed while MEG3 and OTUD4 were lowly expressed in breast cancer cells." (PMID 35109842, 2022). "It was found that OTUD4 had specific binding sites of miR-494-3p and it was down-regulated in breast cancer." (PMID 35109842, 2022). "We also proved that MEG3 overexpression effectively inhibited development of breast cancer cells by targeting miR-494-3p/OTUD4 axis." (PMID 35109842, 2022). "Rescue experiments were also used to test the regulatory effect of miR-494-3p/OTUD4 on breast cancer development." (PMID 35109842, 2022). "However, the functional interplay between OTUD4 and epigenetic regulators during breast cancer metastasis remains inadequately explored." (PMID 41297414, 2025). "Similarly, in vitro cell experiments also indicated that OTUD4 mRNA in breast cancer cell lines was remarkably lower than that in normal cell line." (PMID 35109842, 2022). "Finally, CCK-8, wound healing and Transwell assays were done for detection of influences of miR-494-3p/OTUD4 axis on breast cancer cell viability, migration, and invasion." (PMID 35109842, 2022). "To further test whether OTUD4 regulates the TGFβ pathway in breast cancer we knocked down OTUD4 in the breast cancer cell lines MCF7 and MDA-MB-231." (PMID 32973272, 2020). "Pharmacological blockade of interaction of OTUD4 and CD73 promotes tumor immunogenicity and inhibits tumor progression in immune-cold breast cancer." (PMID 38530357, 2024). "Conversely, OTUD4 KD in either 4T1 or EO771 murine breast cancer cell lines hindered tumor development compared with the control group." (PMID 38530357, 2024). "To assess whether OTUD4 could directly affect CD73 turnover via its deubiquitinase activity, we engineered MDA-MB468 and MDA-MB231 human breast cancer cell lines with stable OTUD4 expression or knockdown (KD)." (PMID 38530357, 2024). "To ascertain whether the physiological relevance for the accumulation of CD73 is regulated by OTUD4, we evaluated adenosine production in both human and mouse TNBC breast cancer cells (MDA-MB231, MDA-MB468, 4T1, and EO771)." (PMID 38530357, 2024).
breast carcinoma (continued). "MEG3 could up-regulate OTU deubiquitinase 4 (OTUD4) and RNA binding motif single-stranded interacting protein 3 (RBMS3) by sponging miR-494 and miR-141-3p, respectively, thereby suppressing breast cancer cells proliferation." (PMID 36551518, 2022). "However, when looking at the correlation between TET2 expression and antiviral response genes in breast cancer patients, a positive correlation was found only for EIF2AK2, MAVS, OTUD4, ABCE1, and RNase L expression levels." (PMID 35351824, 2022). "However, the mechanism of OTUD4 in breast cancer has not been reported." (PMID 35109842, 2022).
ovarian tumor (8 papers, 2015 to 2026). "Ovarian tumor family deubiquitinase 4 (OTUD4) is a member of the ovarian tumor-associated protease domain (OTUDs) family." (PMID 41930143, 2026). "OTU deubiquitinase 4 (OTUD4) is a deubiquitinase that belongs to the Ovarian tumor-associated proteases domain-containing proteins (OTUDs) family." (PMID 38429268, 2024). "As a member of the ovarian tumor (OTU) family and an enzyme that cleaves K48-linked polyubiquitin chains, OTUD4’s impact on SHBs was a key focus of our study." (PMID 40277358, 2025). "OTU domain-containing protein 4 (OTUD4) is a de-ubiquitylating enzyme (DUB) belonging to the ovarian tumor (OTU) family." (PMID 31138677, 2019). "CG3251 and the product of the Drosophila ovarian tumour (otu) gene, Otu, are considered as shared homologues of the human DUB OTUD4." (PMID 26588485, 2015). "We have discovered that the two Drosophila melanogaster homologues of human OTUD4, CG3251 and Otu, contain a serine instead of a cysteine in the catalytic OTU (ovarian tumor) domain." (PMID 26588485, 2015). "Thus, Pearson correlation analysis between the expression level of B4GALT5 and OTU (ovarian tumour) family deubiquitinases (OTUB1, OTUB2, OTUD1, YOD1, OTUD3, OTUD4, OTUD7B) was performed." (PMID 36611197, 2023).
Ataxia (7 papers, 2013 to 2025). Ataxia refers to impaired coordination of voluntary muscle movement. "As an OTU DUB family member, ovarian tumor family deubiquitinase 4 (OTUD4) is implicated in zebrafish embryonic development and is associated with Ataxia, Dementia, and Hypogonadotropism of human patients." (PMID 38215174, 2024). "A previous study reported that OTUD4 homozygous mutation was found in patients with ataxia and hypogonadotropic hypogonadism." (PMID 31011293, 2019). "Homozygous mutations in the OTUD4 gene have been found together with mutations in a ubiquitin-E3-ligase in a familial form of Gordon Holmes syndrome, leading to hypogonadotropism, ataxia and dementia." (PMID 31138677, 2019). "Currently, POLR3A, POLR3B, OTUD4, STUB1, PNPLA6, and RNF216 are all genes associated with CHH syndromes and cerebellar ataxia, with clinical manifestations that can vary and may present with infant or adult onset." (PMID 40508017, 2025).
lung cancer (7 papers, 2019 to 2025). A malignant neoplasm involving the lung. "OTUD4 inhibits the proliferation, migration, and invasive ability of breast, liver, and lung cancer cells by promoting apoptosis and inhibiting the AKT signaling pathway." (PMID 41050073, 2025). "Collectively, these results reveal a mechanism that suppresses TNF-induced NF-κB signaling and links OTUD4 dysfunction to inflammation-driven oncogenesis, including non–small cell lung cancer." (PMID 41062071, 2025). "The current literature alludes to the possibility of OTUD4 being a tumour suppressor in lung cancer, liver cancer and breast cancer." (PMID 32973272, 2020). "Clonogenic formation assay showed that overexpression of OTUD4 significantly decreased colonies formation efficiency after IR treatment, which means that overexpression of OTUD4 did increase radiosensitivity of lung cancer cells." (PMID 31011293, 2019). "Besides, OTUD4 restrained the growth of various tumor including breast, liver, and lung cancer through activating tumor cell apoptosis." (PMID 37726265, 2023). "The expression of OTUD4 is significantly down-regulated in various solid tumor tissues, and the upregulation of OTUD4 impedes the proliferation, migration, and invasion of liver, breast and lung cancer cells by suppressing AKT pathway." (PMID 36411454, 2022). "In cellular experiments concerning breast, liver, and lung cancers, it was found that OTUD4 overexpression may inhibit the proliferation, migration, and invasive ability of breast, liver, and lung cancer cells by promoting apoptosis and inhibiting the AKT signaling pathway in cancer cells." (PMID 41050073, 2025). "Moreover, data form published lung cancer patient gene expression profiles (NCBI/GEO/GSE2514, n = 39) also indicated decreased expression of OTUD4 in tumor tissues." (PMID 31011293, 2019).
nasopharyngeal carcinoma (6 papers, 2022 to 2025). A carcinoma arising from the nasopharyngeal epithelium. "OTUD4 enhances the radiosensitivity of nasopharyngeal cancer (NPC) since it can deubiquitinate and stabilize GSDME to induce pyroptosis." (PMID 40607253, 2025). "Consequently, targeting the OTUD4/GSDME pathway to trigger pyroptosis is a novel strategy to improve radiotherapy sensitization of nasopharyngeal carcinoma." (PMID 38104141, 2023). "A recent study demonstrated that OTUD4 deubiquitinated and stabilized GSDME, thereby promoting GSDME-mediated pyroptosis and increasing radiosensitivity in nasopharyngeal carcinoma." (PMID 38104141, 2023).
dementia (5 papers, 2014 to 2024). Loss of intellectual abilities interfering with an individual's social and occupational functions. "Interestingly, a combination of mutations in OTUD4 along with mutations in RNF216, which codes for a ubiquitin ligase, was also found to result in dementia." (PMID 37149835, 2023). "Interestingly, patients with mutations in OTUD4 and the ubiquitin ligase RNF216 also developed dementia in addition to the described symptoms." (PMID 31138677, 2019). "Although all three Gordon Holmes associated genes (RNF216, OTUD4, STUB1) play a role in the ubiquitin system, the presence of dementia and white matter lesions on MRI has so far only been observed with RNF216/OTUD4 mutations, illustrating some phenotypic diversity related to this syndrome." (PMID 25258038, 2014).
glioblastoma (4 papers, 2020 to 2025). The most malignant astrocytic tumor (WHO grade IV). "The Human Protein Atlas database also revealed that the positive rate of OTUD4 in glioblastoma was significantly higher than that in normal human tissues." (PMID 38429268, 2024). "Here, we report that OTUD4 is significantly overexpressed in glioblastoma and is important for cell proliferation, invasion, and clonogenic capacity." (PMID 38429268, 2024). "This suggests that OTUD4 expression corresponds with TGFβ signalling in the majority of tumour types including breast, glioblastoma, and diffuse large B cell lymphoma and may regulate TGFβ signalling in these cancers." (PMID 32973272, 2020). "Accordingly, these results suggest that OTUD4 may serve as a biomarker for glioblastoma and provide a novel therapeutic target for GBM patients." (PMID 38429268, 2024). "To explore the expression of OTUD4 in glioblastoma, we analyzed the TCGA, CGGA, and GlioVis databases and found that compared with matched adjacent normal tissues, the expression level of OTUD4 in glioblastoma tissues was higher, and OTUD4 expression increased with glioma clinical grade deepened." (PMID 38429268, 2024).
Gordon Holmes syndrome (4 papers, 2018 to 2021). "Mutations in the RNF216 (ring finger protein 216) gene alone or in combination with mutations in OTUD4 (OTU deubiquitinase 4), which are involved in ubiquination, are the cause of Gordon Holmes syndrome." (PMID 33917666, 2021). "Homozygous mutations in OTUD4 were found in a familial form of Gordon Holmes syndrome." (PMID 31138677, 2019). "In addition, we generated an siRNA-resistant OTUD4 construct carrying the point mutation found in Gordon Holmes syndrome patients, G398V, and tested this mutant with respect to stress granule formation." (PMID 31138677, 2019).
triple-negative breast carcinoma (4 papers, 2024 to 2026). An invasive breast carcinoma which is negative for expression of estrogen receptor (ER), progesterone receptor (PR), and human epidermal growth factor receptor 2 (HER2). "Multiomic analyses and experimental validation identified the OTUD4/CD73 proteolytic axis as a promising target in treating immune-suppressive triple negative breast cancer (TNBC)." (PMID 38530357, 2024). "The deubiquitinating enzyme OTUD4 functions as an oncogene in various cancers, but its role in triple-negative breast cancer (TNBC) remains unclear." (PMID 41730840, 2026). "•The OTUD4-ZMYND8-DDX3X axis orchestrates spinal metastasis in triple-negative breast cancer." (PMID 41297414, 2025).
hypogonadotropism (3 papers, 2013 to 2019). "Recently, reports have linked mutations in genes involved in ubiquitination (RNF216, OTUD4, STUB1) to ARCA with hypogonadism." (PMID 25258038, 2014).
melanoma (3 papers, 2024 to 2025). A malignant, usually aggressive tumor composed of atypical, neoplastic melanocytes. "OTUD4 contributes to chemotherapy resistance, whereas A20 facilitates melanoma progression via the Akt pathway." (PMID 39678489, 2024). "Melanoma progression involves DUBs such as OTUD4, A20, and USP9X." (PMID 39678489, 2024).
non-small cell lung carcinoma (3 papers, 2019 to 2024). A group of at least three distinct histological types of lung cancer, including non-small cell squamous cell carcinoma, adenocarcinoma, and large cell carcinoma. "OTUD4 has been found to be lowly expressed in non-small cell lung cancer and is able to inhibit proliferation of cancer cells." (PMID 35109842, 2022). "First, the expression of OTUD4 in non-small cell lung cancer was analyzed." (PMID 31011293, 2019).
Viral infections (3 papers, 2022 to 2025). "Viral infections have been noted to induce OTUD4 expression via IRF3/7, which subsequently binds to mitochondrial antiviral signaling protein (MAVS), inhibiting its ubiquitination." (PMID 40277358, 2025). "Next, we employed proximity ligation assay (PLA) to examine the impact of p8 on the interaction between OTUD4 and USP7 during viral infection." (PMID 40208866, 2025).
colitis (2 papers, 2023 to 2025). Inflammation of the colon. "Here we report that OTUD4 deficiency in IECs or Paneth cells leads to resistance to DSS-induced colitis and S.t. infection." (PMID 37193092, 2023). "Interestingly, OTUD4 deficiency in IECs or Paneth cells led to the upregulation of AMPs which might be responsible for the resistance to DSS-induced colitis and S.t." (PMID 37193092, 2023). "Then, we next sought to explore how the SPARC/OTUD4 axis regulated the intestinal epithelial barrier during colitis." (PMID 39888301, 2025). "In conclusion, our findings revealed that SPARC, increased in CD patients and colitis mice, resulted in intestinal barrier damage by directly interacting with OTUD4, and activating the MYD88/NF‐κB/MLCK/MLC2 pathway." (PMID 39888301, 2025). "To investigate the mechanism by which the epithelial OTUD4 regulates DSS-induced colitis, we isolated the IECs from Vil-Cre;Otud4fl/fl and Otud4fl/fl mice that were given 2.5% DSS in drinking water for 2 days and performed transcriptomic sequencing assays." (PMID 37193092, 2023). "A third possibility is that epithelial OTUD4 regulates the production of AMPs during colitis or bacterial infections, while OTUD4 in other types of cells functions in colon cancer progression." (PMID 37193092, 2023). "•Knockout of OTUD4 in Paneth cells suppresses DSS-induced colitis and bacterial infection by promoting AMP-production." (PMID 37193092, 2023). "Here, we report that the ovarian tumor family deubiquitinase 4 (OTUD4) in Paneth cells restricts the expression of AMPs and thereby promotes experimental colitis and bacterial infection." (PMID 37193092, 2023). "Besides, the direct interaction between SPARC and OTUD4 was evidenced in the colonic tissues of DSS‐induced colitis mice." (PMID 39888301, 2025). "Interestingly, we found that Vil-Cre- and Def-Cre- but not Lyz2-Cre-mediated deletion of OTUD4 in the Otud4fl/fl mice alleviated DSS-induced colitis, indicating that OTUD4 in IECs or Paneth cells promotes intestinal inflammation." (PMID 37193092, 2023). "•Knockout of OTUD4 in IECs suppresses DSS-induced colitis and bacterial infection." (PMID 37193092, 2023). "Because OTUD4 negatively regulates the expression of AMPs during DSS-induced colitis, we next investigated whether OTUD4 regulated antibacterial responses in the gut." (PMID 37193092, 2023). "We next examined whether myeloid depletion of OTUD4 affected DSS-induced colitis in mice." (PMID 37193092, 2023).